SOX1 (SRY-box transcription factor 1)
Diseases named in the same sentence as SOX1 in open-access papers (continued):
Sharing a sentence is not in itself a finding about the gene and the disease.
SOX1 also shares sentences with these, for which no sentence is quoted: Ataxia (2 papers); osteosarcoma (2); Achalasia (1); acute kidney injury (1); autoimmune neuropathy (1); benign ovarian tumors (1); Borderline personality disorder (1); cervical adenocarcinoma (1); cervical disease (1); chronic kidney disease (1); Cognitive impairment (1); dementia (1); embryonic carcinoma (1); esophageal cancer (1); Granulocytopenia (1); intraepithelial neoplasia (1); ischemic stroke (1); lung adenocarcinoma (1); lymph node metastasis (1); major depressive disorder (1); memory impairment (1); microcephaly (1); movement disorder (1); multiple myeloma (1); multiple sclerosis (1); myasthenia (1); ovarian teratoma (1); ovarian tumors (1); psychiatric diseases (1); psychosis (1).
A further 10 diseases each share a sentence with SOX1 in 1 paper.